FZD7 (frizzled class receptor 7)
Description:
Receptor for Wnt proteins. Most frizzled receptors are coupled to the beta-catenin canonical signaling pathway, which leads to the activation of disheveled proteins, inhibition of GSK-3 kinase, nuclear accumulation of beta-catenin and activation of Wnt target genes. A second signaling pathway involving PKC and calcium fluxes has been seen for some family members, but it is not yet clear if it represents a distinct pathway or if it can be integrated in the canonical pathway, as PKC seems to be required for Wnt-mediated inactivation of GSK-3 kinase. Both pathways seem to involve interactions with G proteins. Activation by WNT8 induces expression of beta-catenin target genes (By similarity). Following ligand activation, binds to CCDC88C/DAPLE which displaces DVL1 from FZD7 and leads to inhibition of canonical Wnt signaling, activation of G proteins by CCDC88C and triggering of non-canonical Wnt responses. May be involved in transduction and intercellular transmission of polarity information during tissue morphogenesis and/or in differentiated tissues. (Microbial infection) Acts as a receptor for C.difficile toxin TcdB in the colonic epithelium.
Synonyms: FzE3
Tractability: Small molecule: a structure with a bound ligand is known. Antibody: a drug acting on it is in phase 2 or 3 trials; UniProt places it where antibodies can reach, with high confidence; its Gene Ontology location is reachable by antibodies, with high confidence; UniProt predicts a signal peptide or a membrane-spanning region. PROTAC: UniProt records ubiquitination sites on it; ubiquitination databases record sites on it.
Target class: Frizzled family G protein-coupled receptor; Membrane receptor
Gene: Protein-coding gene on chromosome 2 (202,033,855 to 202,038,441, forward strand). Ensembl gene ENSG00000155760.
Subcellular location: Cell membrane; Endosome membrane
Subcellular location (Human Protein Atlas): Vesicles
Pathways (Reactome):
Signal Transduction: Asymmetric localization of PCP proteins; Class B/2 (Secretin family receptors); PCP/CE pathway
Disease: WNT5:FZD7-mediated leishmania damping
Gene Ontology:
Molecular function: frizzled binding; PDZ domain binding; phosphatidylinositol-4,5-bisphosphate binding; protein binding; Wnt receptor activity; Wnt-protein binding; transmembrane signaling receptor activity
Biological process: canonical Wnt signaling pathway; mesenchymal to epithelial transition; negative regulation of cardiac muscle cell differentiation; negative regulation of cell-substrate adhesion; negative regulation of ectodermal cell fate specification; non-canonical Wnt signaling pathway; positive regulation of DNA-templated transcription; positive regulation of epithelial cell proliferation involved in wound healing; positive regulation of MAPK cascade; positive regulation of phosphorylation; regulation of canonical Wnt signaling pathway; regulation of DNA-templated transcription; stem cell population maintenance; cellular response to retinoic acid; neuron differentiation; positive regulation of JNK cascade; Wnt signaling pathway, planar cell polarity pathway; cell surface receptor signaling pathway
Cellular component: endosome membrane; plasma membrane; recycling endosome membrane; membrane
Genetic constraint (gnomAD): Loss-of-function variants: 21 observed, 38.7 expected, observed/expected ratio (o/e) 0.54, 90% interval 0.38 to 0.78. The upper end of that interval is the gene's LOEUF score, 0.78, which puts it in group 3 of 6, group 1 being the genes least tolerant of losing a copy. Missense variants: 695 observed, 844.69 expected, observed/expected ratio (o/e) 0.82, 90% interval 0.77 to 0.88. Synonymous variants: 428 observed, 388.42 expected, observed/expected ratio (o/e) 1.1, 90% interval 1.02 to 1.19.
Homologues: Orthologues: chimpanzee FZD7 (100% identical), macaque FZD7 (99% identical), dog FZD7 (98% identical), pig FZD7 (97% identical), guinea pig FZD7 (97% identical), mouse Fzd7 (97% identical), rat Fzd7 (97% identical), rabbit FZD7 (96% identical), tropical clawed frog fzd7 (84% identical), zebrafish fzd7a (79% identical), zebrafish fzd7b (78% identical), Drosophila melanogaster fz3 (24% identical). Paralogues in human: FZD1 (77% identical), FZD2 (77% identical), FZD5 (48% identical), FZD8 (47% identical), FZD10 (45% identical), FZD3 (43% identical), FZD9 (41% identical), FZD4 (41% identical), FZD6 (41% identical), SMO (27% identical), FRZB (16% identical), SFRP4 (16% identical), and 3 more.
Diseases named in the same sentence as FZD7 in open-access papers:
FZD7 is named in the same sentence as 115 diseases in open-access papers, as found by Europe PMC text mining. Sharing a sentence is not in itself a finding about the gene and the disease. The quoted sentences say what the papers report.
breast cancer (39 papers, 2007 to 2025). A primary or metastatic malignant neoplasm involving the breast. "MMTV-Wnt1 mice carrying the wild type (WT) or the HF7 allele of Fzd7 developed mammary tumors with similar latencies." (PMID 41218118, 2025). "These tumors express high levels of Fzd7 in the basal compartment, a cell population associated with breast cancer initiation." (PMID 41218118, 2025). "Low expression of FZD7 is associated with better clinical prognostic parameters and clinical survival for breast cancer." (PMID 36276155, 2022). "In fact, the overexpression of FZD7 was detected in 90% of tumors (most in the human hepatocellular carcinoma cells and in breast cancer cells) where causes the accumulation of β-catenin protein affecting the Wnt/β-catenin signal transduction pathway." (PMID 34830379, 2021). "Elevated levels of FZD7 protein in human breast cancer were associated with unfavorable prognosis and progressive stages of disease." (PMID 26716419, 2016). "Because FZD7 was expressed in both cells lines, been previously implicated in breast cancer malignancy, and appeared to be a target in pilot studies, we focused on this FZD member exclusively in this study." (PMID 24897117, 2014). "Here, we describe for the first time an important functional link between SIRT1 and FZD7, which has recently been implicated in breast cancer pathogenesis." (PMID 24897117, 2014). "FZD1/2/7 form a subgroup with nearly identical CRDs within the FZD family and FZD7 has been previously shown to be associated with triple-negative breast cancer and targeting FZD7 may reduce growth of breast cancer cells." (PMID 37943878, 2023). "Using the MMTV-Wnt1 genetically engineered mouse model, which develops mixed-lineage mammary tumors resembling triple-negative breast cancer and composed of both basal and luminal subtypes, we identify the frizzled class receptor 7 (Fzd7) as a key player." (PMID 41218118, 2025). "By overcoming the limitations of prior WNT/FZD-targeted therapies, this work positions FZD7 as a promising therapeutic entry point in aggressive breast cancers." (PMID 41218118, 2025). "Fzd7 is expressed on mammary tumor cells that show enhanced tumorigenic potential in both orthotopic transplantation and tumor organoid assays." (PMID 41218118, 2025). "For example, miR-1 has been shown to inhibit FZD7 in breast cancer cells and Wnt1 ligand in the sea urchin." (PMID 38721525, 2024). "We found that COL1A1, MMP3, PDGFR and FZD7 were significantly increased/decreased in breast cancer brain metastasis compared with primary breast cancer, and the four genes were also acted as long-term outcome factors in breast cancer brain metastasis." (PMID 39157383, 2024). "Functionally, levels of Fzd7 were directly proportional to the mammosphere formation capacity of breast cancer cell lines." (PMID 37804416, 2024). "The expression of the FZD7 gene in several clinical parameters in breast cancer patients was evaluated using BC-GenexMiner V4.3 software." (PMID 36276155, 2022). "The expression level of FZD7 in ER-/PR-breast cancer patients was significantly higher than that in other groups in (P <0.0001)." (PMID 36276155, 2022). "The high expression of the FZD7 gene in breast cancer was confirmed in this study, which used BC-GenexMiner V4.3 software to assess the expression of numerous clinical factors of the FZD7 gene in breast cancer patients." (PMID 36276155, 2022). "In breast cancer, γ-tocotrienol, a vitamin E compound, acts as a chemopreventive agent by reducing the expression of FZD7, increasing expression of canonical WNT signaling inhibitors, and reversing EMT." (PMID 34604862, 2021).
breast cancer (continued). "In mouse model of basal-type breast cancer tumorigenesis, ΔNp63 can govern the tumor-initiation activity of breast cancer cells by directly driving FZD7 expression to enhance WNT signaling pathway." (PMID 32549764, 2020). "FZD7 has been showed as up-regulated in a variety of cancer types including colorectal cancer, hepatocellular carcinoma, and certain breast cancer subtypes." (PMID 31429720, 2019). "A study revealed that inhibitors of SIRT1/2 reduce FZD7 expression in breast cancer cell lines by decreasing β-catenin enrichment at the FZD7 promoter and that silencing FZD7 suppressed breast cancer cell migratory ability and cell growth." (PMID 29361730, 2018). "ΔNp63, an isoform of p63, regulates both normal mammary stem cell activity and tumor initiating activity of breast cancer by increasing FZD7 expression by binding in a conserved active enhancer region of FZD7." (PMID 29789460, 2018). "A screen to analyse which pathways were active in triple negative (TN) breast cancer, identified that the Wnt pathway was an important driver in this aggressive type of breast cancer and that FZD7 was often overexpressed." (PMID 27196929, 2016). "FZD7, among the ten known human Frizzled receptors, is the most commonly dysregulated Wnt receptor in various cancers including colorectal cancer, breast cancer and hepatocellular carcinoma." (PMID 27852064, 2016). "Once we had established some link between, β-catenin, c-Jun, and the FZD7 gene, we wanted to determine the physiological consequence of altered FZD7 expression in breast cancer cells." (PMID 24897117, 2014). "To determine the relative change in FZD7 gene, we performed real-time PCR analyses (RT-qPCR) in both breast cancer cell lines following treatment with either 50 μM or 100 μM of cambinol." (PMID 24897117, 2014). "Fzd7 also plays a key role in the development of breast cancer." (PMID 40230079, 2025). "In this study, we establish FZD7 as a defining marker of tumor-initiating basal cells in MMTV-Wnt1-driven breast cancer, a well-characterized model of TNBC, a highly aggressive breast cancer subtype with poor prognosis and high risk of recurrence and metastasis." (PMID 41218118, 2025). "Importantly, in both the METABRIC and TCGA breast cancer datasets, FZD7 consistently exhibits higher mRNA levels than the other 3 FZDs in basal-like breast cancers." (PMID 37943878, 2023). "In addition, it has been reported that propofol inhibits cervical cancer progression by regulating the HOTAIR/miR-129-5p/RPL14 axis and HOTAIR promotes breast cancer progression by regulating the miR-129-5p/FZD7 axis." (PMID 36115953, 2022). "COL6A1 mediates Fzd7-Wnt5b to induce breast cancer mesenchymal-like stemness." (PMID 36167487, 2022). "The canonical WNT signaling pathway mediated by FZD7 can promote breast cancer stem cell activity." (PMID 35854234, 2022). "FZD7 gene expression was higher in PATIENTS with HER2-negative breast cancer (P <0.0001)." (PMID 36276155, 2022). "As a receptor of the Wnt/β-catenin signal, FZD7 has been shown to be highly expressed in a variety of cancers, including gastric cancer and breast cancer, and is involved in regulating cancer cell proliferation, migration, and invasion via the activating Wnt/β-catenin pathway." (PMID 31399111, 2019). "In addition, an elegant study from Yibin Kang’s group recently demonstrated a separate regulatory mechanism of FZD7 in human mammary stem cells (MaSCs) and TN breast cancer cells." (PMID 27196929, 2016). "Furthermore, recent research has revealed a novel mechanism by which FZD7 expression is regulated in breast cancer cells." (PMID 27196929, 2016). "So to test whether β-catenin was involved in FZD7 expression in breast cancer cells, we performed chromatin immunoprecipitation (ChIP) followed by quantitative PCR (ChIP-qPCR)." (PMID 24897117, 2014).
breast cancer (continued). "Nevertheless, these findings suggest that selective inhibition of FZD7-mediated signaling is sufficient to exhibit an inhibitory effect on growth of tumor cells, although Wnt signaling is not likely a driving force but rather one of the contributing factors in tumorigenesis of human breast cancers." (PMID 37943878, 2023). "As such, genetic and/or pharmacological inhibition of SIRT1 significantly reduced FZD7 levels through perturbing the binding of β-catenin and c-Jun transcription factors to the endogenous FZD7 promoter, reversing the potent tumourigenic effect of FZD7 overexpression in breast cancer cells." (PMID 27196929, 2016). "For instance, Fzd7 expression correlated with stemness-related genes (CD44, LGR5, NOTCH2, EGFR, IL6, TNC, ANTXR1) in breast cancer." (PMID 37804416, 2024). "On the other hand, TCF7L2, ARRB1, DLL1, FZD7, HES1, and JAG1 transcript levels were significantly lower in breast cancer tissues than in normal samples (p < 0.0009, p = 0.0131, p = < 0.0001, p = < 0.0001, p = 0.0138, and p < 0.0001, respectively)." (PMID 36476410, 2022). "hsa-miR-27b-3p directly targets HSP90AA1 and Fzd7 in NSCLC, ROR1 in gastric cancer, and CBLB/GRB2 in breast cancer to suppresses cell proliferation, migration, invasion, and expression of MET." (PMID 34603447, 2021). "Our independent analysis of primary ER+PIK3CA-mutant breast cancers, which exhibit high INPP4B expression, identified these and additional upregulated Wnt genes (LEF1, MYCN, FZD7, SFRP2, TCF7L1, CTNNB1, FZD4, and SFRP1)." (PMID 34035258, 2021). "When FZD7 is inhibited by an antibody coated nanoshell in breast cancer cells, the EMT phenotype is reduced, identifying FZD7 as targetable in cancer cells and offering a potential delivery approach for FZD7 chemoprevention." (PMID 34604862, 2021). "In breast cancer cells, inhibition of SIRT1/2 decreased Frizzled7 (FZD7) protein expression, as well as β‐catenin and c‐Jun binding to the FZD7 promoter." (PMID 28994177, 2017). "Although FZD7 is up-regulated in multiple tumors, including colorectal cancer and breast cancer, we found FZD7 is down-regulated in PCa relative to normal tissue across multiple cohorts." (PMID 29416676, 2018). "PIK3CA mutant ER+ breast cancers exhibit an RNA expression profile of enhanced Wnt/β-catenin signaling, including up-regulation of Wnt target genes (AXIN2, LEF1, MYCN) and other components such as transcriptional regulators (TCF7L1, TCF7L2, CTNNB1), receptors (FZD4, FZD7) and ligands (WNT5A)." (PMID 37471270, 2023). "Importantly, FZD7 or ΔNp63 depletion, exerts a similar effect on tumorpheres formation, suggesting that activation of the WNT signaling is a critical effector of the ΔNp63-dependent control of breast cancer stemness, at least in basal-type breast cancer." (PMID 31159154, 2019). "Our gene expression data also support a role in ST-3 activation of Wnt-signalling components, such as FZD7 and DVL3, which is in line with the activation of the Wnt pathway by ST-1/MMP-3 via E-cadherin cleavage, resulting in EMT and thus enhanced invasive properties of mammary tumour cells." (PMID 17233884, 2007). "Ueno and colleagues demonstrated that FZD7 expression is important for cell survival in colorectal cancer; however the role that SIRT1 plays had not been explored in breast cancer cells." (PMID 24897117, 2014).
hepatocellular carcinoma (34 papers, 2009 to 2025). A malignant tumor that arises from hepatocytes. "LncRNA associated with poor prognosis of hepatocellular carcinoma (AWPPH) promotes TNBC growth by upregulating the frizzled homolog 7 (FZD7) ligand of the Wnt pathway and decreased manifestation of lncRNA has been reported to increase the malignant spread of TNBCs." (PMID 35814205, 2022). "For instance, it reverses docetaxel resistance in prostate cancer through the androgen receptor and PI3K/Akt signaling pathway, and reverses multi‐drug resistance in hepatocellular carcinoma cells through the FZD7/β‐catenin pathway." (PMID 41368332, 2025). "Overexpression of FZD7 in cancer cells (e.g., intestinal cancer, hepatocellular carcinoma, and breast cancer) often results in increased cell proliferation and tumor growth." (PMID 36620565, 2022). "Two human hepatoma cell lines, HepG2 and Huh-7 with high expression levels of FZD7 were selected to test the efficacy of Fz7-21 as an antagonist of Wnt/β-catenin signaling." (PMID 35453784, 2022). "Further, the efficacy of the soluble Fzd7 has been taken into consideration and assessed thus far in two types of cancer, hepatocellular carcinoma (HCC) and triple breast cancer cells (TNBC)." (PMID 35655594, 2022). "Our studies above are in agreement with previously reported Wnt3-Fzd7 binding in intestinal stem cells and the functional interaction between Wnt3 and Fzd7 in hepatocellular carcinoma cells." (PMID 33525513, 2021). "Hepatocellular carcinoma mainly displays CTNNB1 mutations (20–35%), AXIN1 mutations (8–15%), and Frizzled-7 (FZD7) overexpression (90%)." (PMID 33291655, 2020). "In particular, FZD7 activates Wnt/β-catenin signaling in hepatocellular carcinoma, colon cancer and TNBC (triple negative breast cancer) cells." (PMID 31671889, 2019). "In hepatocellular carcinoma, Sox9 activates the canonical Wnt pathway through direct binding with Fzd7." (PMID 28279198, 2017). "In hepatocellular carcinoma cells, the functional interaction between Wnt3 and FZD7 enhances proliferative rate." (PMID 26716419, 2016). "The expression level of FZD7 was found up-regulated in several malignant tumors, such as colorectal cancer, hepatocellular carcinoma, esophageal cancer, lung cancer and gastric cancer, etc." (PMID 26716419, 2016). "The expression of genes encoding proteins known to be associated with the cell cycle (E2F1), adhesion and proteolysis (OPCML) and hepatocellular carcinoma (FZD7, IGFBP1 and LEF1) was elevated 3- to 9-fold." (PMID 26442469, 2015). "Similarly, a soluble extracellular peptide of FZD7 has been utilized as a decoy receptor for inhibiting FZD7 in hepatocellular carcinoma cells." (PMID 36620565, 2022). "In addition, the functional interaction between Wnt3 and Fzd7 led to the activation of the Wnt/β-catenin signaling pathway in hepatocellular carcinoma cells." (PMID 33525513, 2021). "miR-27a could reverse multiple drug resistance in hepatocellular carcinoma cells by inhibiting the FZD7/β-catenin pathway." (PMID 29137318, 2017). "MicroRNA 27a could function to reverse multiple drug resistance by inhibiting FZD7/beta-catenin pathway in hepatocellular carcinoma and therefore promote the therapeutic effect in patients receiving chemotherapy in Chen's study." (PMID 29100439, 2017). "Fzd7 was upregulated in hepatocellular carcinoma (HCC), resulting in activation of β-catenin pathway, accompanied by increased TCF transcriptional activity and cell proliferation rate." (PMID 32894152, 2020). "FZD7 is the Wnt receptor most commonly up-regulated in a variety of cancers including colorectal cancer, hepatocellular carcinoma (HCC) and triple negative breast cancer." (PMID 26056595, 2014). "Accumulating evidence has confirmed that FZD7 can mediate the activation of the canonical WNT/β-catenin signaling in breast, colorectal, and hepatocellular carcinoma." (PMID 35854234, 2022). "In hepatocellular carcinoma, DSCR8 increases Fzd7 expression by sequestering miR-485-5p." (PMID 34671643, 2021).